STAT3 (signal transducer and activator of transcription 3)
Diseases named in the same sentence as STAT3 in open-access papers (continued):
Sharing a sentence is not in itself a finding about the gene and the disease.
tumor (continued). "However, targeting STAT3 in the whole tumor microenvironment, including tumor-associated myeloid cells, was shown to generate potent antitumor effects independently from PTEN status of cancer cells." (PMID 34067832, 2021). "Previous studies indicated that STAT3 could promote tumor progression and was associated with the efficacy of targeted therapy." (PMID 34195079, 2021). "However, there are data demonstrating that STAT3 is able to elicit different responses according to the type of tumor and the mutational status." (PMID 34440220, 2021). "STAT3 signalling is considered a major pathway for cancer inflammation due to its frequent activation in malignant cells and key role in regulating many crucial genes associated with inflammation in the tumour microenvironment." (PMID 34361105, 2021). "According to a recent report, CSCs could recruit tumor-associated macrophages (TAMs) and induce their polarization via different chemokines (IL-4 and IL-13) and signal pathways (Wnt, STAT3 and NF-kB)." (PMID 34638298, 2021). "It will be interesting to see whether the specific direction of the STAT3 inhibitor to tumor-promoting macrophages reduces the risk of autoimmune side effects of STAT3 inhibition as previously reported." (PMID 32752088, 2020). "Apigenin was demonstrated to inhibit inflammation and inflammation-induced carcinogenesis by suppressing STAT3 and NF-κB signalling in vivo, and showed a protective effect against colitis-associated cancer by reducing the tumour volume in addition to decreasing neutrophil infiltration." (PMID 32731620, 2020). "Importantly, STAT3 activation has been documented in several tumor types and is associated with tumorigenesis." (PMID 32012950, 2020). "In vivo, the combination of two drugs significantly decreased intraperitoneal tumour burden and ascites volume, prolonged survival of tumour‐bearing mice compared with each monotherapy; these results were associated with downregulation of phospho‐Stat3 and activation of apoptosis pathway." (PMID 31778258, 2020). "Thus, these PD-1/miRNA/STAT3 pathways provided a new idea of treatment idea for hindering MDSC-associated tumor metastasis." (PMID 33613512, 2020). "The affinity of CTLA4apt (aptamer to CTLA4) to STAT3 small interfering RNA (CTLA4apt-STAT3 siRNA) may sharply decrease the number of tumor-associated CD4+ regulatory Tregs." (PMID 33050544, 2020). "Thus, STAT3 loss within this model resulted in the formation of a mesenchymal-like tumor phenotype, known to be associated with drug resistance and metastasis." (PMID 32365499, 2020). "Additionally, upregulated STAT3 was associated with advanced tumor stage, and patients with stage 4 tumors had higher STAT3 levels." (PMID 32296013, 2020). "Moreover, STAT3 is strongly linked to tumor angiogenesis and metastasis and is related to poor prognosis in different tumors." (PMID 32664527, 2020). "In fact, many of the products from TAM and neutrophils in the TME are known to upregulate or downregulate activation of NF-κB and Stat3 in cancer cells, further highlighting the crosstalk between tumor-associated innate immunity and dysregulated iron metabolism in cancer cells." (PMID 33679721, 2020). "Many of the STAT3 target genes, including the genes encoding Bcl-XL, Survivin, Hsp70, Cyclin D1, c-Myc, etc., have been shown to be upregulated during tumor formation, which may be responsible for mediating CAC." (PMID 33082817, 2020). "Furthermore, STAT3 activation in lymphocytes is associated with T cell impaired functions and reduced anti-tumor activity." (PMID 32150944, 2020). "Furthermore, the expression of STAT3 in tumor-associated leukocytes also plays a key role in immune modulation." (PMID 33143283, 2020).
tumor (continued). "In addition, we also found that enalapril and 5-FU together significantly inhibited the expression of MMP-2 and MMP-9 in vivo, which are also associated with tumor invasion and metastasis, and are regulated by NF-κB/STAT3 pathway." (PMID 32581212, 2020). "This decrease in STAT3 activity and expression caused by cucurbitacin B paves the way for a reduction in the proliferation of GC cells and their sensitization into the anti-tumor activity of cisplatin as a chemotherapeutic agent." (PMID 32545648, 2020). "Activation of STAT3 has been shown to contribute to tumor-associated immunosuppression." (PMID 32312954, 2020). "Notably, several studies have demonstrated that STAT-3 activation in tumor cells and tumor-associated immune cells promotes cancer metastasis via EMT." (PMID 32391271, 2020). "Aberrant expression of STAT3 has been implicated in malignant transformation and tumor progression." (PMID 33390934, 2020). "STAT3 activation in immune cells is indeed associated with suppression of anti-tumor immunity." (PMID 32150944, 2020). "The administration of ODZ10117 dramatically decreased the tumor population and the levels of active STAT3, CSC markers such as NESTIN and SOX2, and MES-associated genes FN and ITGAV without significantly affecting the body weight compared to the vehicle-treated control group." (PMID 32183406, 2020). "Furthermore, the activation of STAT3 in tumor cells was reported to cause resistance to anticancer therapies, such as radiotherapy and chemotherapy." (PMID 32256354, 2020). "It has been shown that STAT3 is constitutively active in tumor-associated B cells." (PMID 33335857, 2020). "Reduced levels of SOCS3 may cause the hyperactivation of STAT3, which induces multiple tumor-promoting genes and, hence, contributes to malignancies and carcinogenesis." (PMID 32679860, 2020). "IL-6/STAT3 is an important signaling pathway related to lncRNAs-caused tumor metastasis." (PMID 33520725, 2020). "Whether STAT3 downregulation in tumor-associated immune cells is mediated by the CBD agonist or inverse agonist effects on CB2 receptors needs to be further investigated." (PMID 33143283, 2020). "Moreover, the canonical transcription factors that mediate the functions of some of the mediators, namely NF-κB and STAT3, were generally implicated in generating tumor cell plasticity or maintaining it at different stages of the malignancy cascade." (PMID 33585241, 2020). "However, the administration of ODZ10117 suppressed the tumor population and levels of active STAT3 and tumor growth-associated factors and increased the level of active caspase-3, indicating the effective anti-tumor effect of ODZ10117." (PMID 32183406, 2020). "In HPV associated tumor cells, STAT3 expression may be indirectly activated by NFκB, since IL-6 is a transcription target of the later and known activator of the STAT3 pathway." (PMID 33330068, 2020). "In tumor model, downregulation of miR-21 was associated with downregulation of STAT3." (PMID 31641939, 2020). "Importantly, STAT3 was correlated with immune infiltration and particularly regulated tumor-associated macrophage (TAM), M2 macrophage, T-helper 1 (Th1), follicular helper T (Treg), and exhausted T-cells." (PMID 32486001, 2020). "It has been confirmed that the α7 nicotinic acetylcholine receptor of tumor-associated macrophages could inhibit the metastasis of COAD through the JAK2/STAT3 signaling pathway." (PMID 32850813, 2020). "We uncovered a novel oncogenic pathway with broad biological and clinical relevance involving loss of miR-204-5p with activation of EMT and STAT3 signaling, which revealed the mechanisms governing tumor-initiating and metastatic properties and provided a novel therapeutic target for HNSCC." (PMID 31938073, 2020).
tumor (continued). "Finally, a thorough study of the signaling pathway responsible for this effect underlined the IDO/Kyn/AhR cascade and serine-phosphorylation of STAT3 as the effectors, providing new insights into tumor dormancy mechanisms associated with IFNs." (PMID 32296435, 2020). "STAT1 plays an important role in growth arrest and promoting apoptosis, and is implicated as a tumor suppressor; while STAT3 suppresses apoptosis and promotes tumor cell proliferation, and plays a critical role in the invasion and metastasis of malignant tumors." (PMID 33361763, 2020). "Moreover, the altered p‐STAT3 expression is associated with angiogenesis and has been considered a new therapeutic target to inhibit tumor growth and angiogenesis." (PMID 30950039, 2019). "However, persistently activated STAT3 signaling is closely associated with oncogenic signaling and is frequently observed in numerous types of cancer cells and tumor tissues of cancer patients." (PMID 31684051, 2019). "Finally, we showed the inhibition of the STAT3 expression, a key protein implicated in the regulation of growth, survival, invasion, migration and metastatic spread of tumour cells." (PMID 31801187, 2019). "STAT3 is not only overexpressed and activated in cancer cells but also in tumor-associated immune cells, inducing the expression of immune-suppression related genes, including IL-6, IL-10, TGF-β and VEGF and driving the escape of cancer cells from immune-mediated elimination." (PMID 31088482, 2019). "Additionally, capsazepine treatment caused reduction in phosphorylation of STAT3 and increased PTPε protein levels in tumor tissues." (PMID 30871017, 2019). "However, it has been reported that hypoxia-induced autophagy has attenuated the effects of immunotherapy by impairing CTLs-mediated tumor cell lysis associated with the hypoxia-dependent phosphorylation of STAT3 (pSTAT3)." (PMID 30678689, 2019). "Moreover, inflammation triggers signaling pathways, such as STAT3 (Signal transducer and activator of transcription 3) and β-catenin, which causes proliferation and remodeling of epithelial cells and then promotes tumor growth." (PMID 31013961, 2019). "Accumulating evidence suggests that M2 macrophages activated by cancer cells could promote activation of STAT3, triggering secretion of several cytokines (IL-6 and IL-10) and this eventually causes increased tumor growth and metastasis." (PMID 30791624, 2019). "Moreover, the rate of tumor cell proliferation was decreased in CARD9-deficient mice, and the tumor cell-intrinsic activation of STAT3 was substantially reduced." (PMID 30906296, 2019). "We have shown that tumor-derived exosome (TDE)-associated HSP70 led to STAT3 activation in MDSCs." (PMID 31480382, 2019). "As STAT3 is a pivotal regulator of cellular metabolism under physiological conditions, an ideal STAT3-targeted agent should minimize its toxicities in normal cells while preserving its specificity and efficacy against tumor-associated components." (PMID 31731457, 2019). "Moreover, STAT3 signaling within tumor-associated macrophages and neutrophils drives secretion of factors that facilitate metastasis and suppress immune cell function." (PMID 31684144, 2019). "As the protein expression level and biological effect of the anti-apoptotic factors MCL1 and survivin (BIRC5) have been associated with phosphorylation of STAT3 in tumor cells, we examined the protein expression level of STAT3 target genes, including MCL1 and survivin." (PMID 31287013, 2019). "The PI3K/Akt and the STAT3 pathways are functionally associated in many tumor types." (PMID 30622697, 2019). "Notably, STAT3 activation in cancer cells and cells of the tumor microenvironment has been linked to tumor promotion, suppression of anti-tumor immunity, and the inflammatory response in the tumor microenvironment." (PMID 31878193, 2019).
tumor (continued). "Hyperactivation of STAT3 in malignant cells and tumor-associated immune cells promotes cancer survival and growth through expression of anti-apoptotic and proliferative genes, as well as cytokines that generate an immunosuppressive tumor microenvironment." (PMID 31671769, 2019). "Studies have shown that PD-L1 expression can be induced by extrinsic stimulation such as interferon-gamma produced by surrounding tumor cells, and by the activation of intrinsic oncogenic pathways, such as STAT3, an activating EGFR mutation or ALK translocation." (PMID 30961670, 2019). "It has been hypothesized, that SNPs in STAT3 gene may influence STAT3 expression, activation upon stimulation and contribute to predisposition to inflammatory and neoplastic diseases." (PMID 31342143, 2019). "Studies also found adaptive reactivation of signal transducer and activator of transcription 3 (STAT3) within the minimal residual surviving drug persister tumor cells, which was co-activated with the SRC-YES-associated protein 1 (YAP1) pathway in EGFR-mutant NSCLC." (PMID 31815659, 2019). "This study associates aggressive tumor behavior and acquirement of mesenchymal-like phenotypes with the loss of STAT3 function, while persistent STAT3 activation bestows a differentiated epithelial morphology to cells that can affect their potential for tumorigenesis." (PMID 32039025, 2019). "It was speculated that STAT3-dependent effector molecules such as IDO are induced in tumor-associated MDSCs." (PMID 31083487, 2019). "In addition, STAT3 is associated with tumor cell apoptosis through the regulation of BCL2, BAX, MCL1 and survivin (BIRC5)." (PMID 31287013, 2019). "Interestingly, our previous studies demonstrated that high activated phospho-STAT3 (Ser727) expression is associated with advanced tumor stage in UTUC tissues and can predict poor prognosis in advanced-stage UTUC patients." (PMID 31565097, 2019). "The underlying molecular mechanisms may be associated with the induction of tumor cell apoptosis by inhibition of the STAT3/Bcl-2 signal pathway." (PMID 31777595, 2019). "At the same time, specific genetic changes present at GB subsets such as PTEN-deficiency, may alter STAT3 function to exhibit a tumor suppressor potential." (PMID 31698775, 2019). "Persistent activation of STAT3, in addition to tumor cell proliferation and differentiation and metastasis, promotes the expression of related immunosuppressive factors, which causes immunosuppression of the tumor microenvironment." (PMID 31885639, 2019). "Similarly, genetic variants of the genes encoding elements of IL-6/JAK/STAT3 pathway were related to the risk, course, prognosis and response to treatment of different neoplasia, but available data concerning BCC are scarce." (PMID 31342143, 2019). "Activating mutations in oncogenic RAS/BRAF/MEK pathways trigger a tumor-intrinsic inflammatory network with the concerted regulation of master transcription factors (TFs) including STAT3, NF-κB and AP-1 which in turn trigger the expression of cytokines, including IL-6, IL-1, IL-10, TNF and VEGF." (PMID 31766350, 2019). "Also, mice reconstituted with Stat3-deficient immune cells can generate a potent anti-tumor immune response." (PMID 31388334, 2019). "STAT3 has close association with inflammation which is subsequently linked with tumor initiation due to mutation in genetic makeup of malignant cells, in addition to this different environmental influences such as, stress, carcinogenic agents, smoking and radiations." (PMID 30847297, 2019). "IL-6/STAT3 signaling cascade induces many downstream targets and its dysregulation could contribute to initiation, promotion, and progression of tumor-associated inflammation." (PMID 29385191, 2018). "CCP initiates a complete cycle by causing inhibition of STAT3 in the tumor-associated microglia." (PMID 30041669, 2018).
tumor (continued). "However, the patients with high STAT3 tumor had a significantly higher risk of both disease progression (p = 0.009) and cancer-specific mortality (p = 0.009), but not with tumors expressing S1PR1 or IL-6." (PMID 30091994, 2018). "IL-6’s activation of STAT3 appears to protect the epithelium of the GI tract from apoptosis and stimulates regeneration, and high IL-6 levels have been associated with increased colorectal cancer tumor risk." (PMID 30038723, 2018). "Constitutively active STAT3 has been shown to increase levels of tumor-associated signaling molecules such as survivin, Bcl-XL, cyclin D1/D2, C-Myc, Mcl-1, and vascular endothelial growth factor (VEGF), leading to increased cell proliferation, cell survival, angiogenesis, and oncogenesis." (PMID 30446007, 2018). "Nonetheless, targeting the common and functionally well-defined STAT3 in genetically stable, tumor-associated myeloid cells provides for a broadly applicable immunotherapeutic strategy that could overcome the limitations of current cancer immunotherapies." (PMID 29921770, 2018). "In addition, STAT-3 activation has also been associated with the resistance of tumor cells to chemotherapeutic agents and γ radiation." (PMID 30373171, 2018). "Tumor-promotion is associated with production of cytokines by immune/inflammatory cells that activate transcription factors, such as NF-κB (nuclear factor kappa B), STAT3 (Signal Transducer and Activator of Transcription 3), and AP-1 (activator protein 1)." (PMID 30213077, 2018). "In addition, NF-κB and STAT3 induce chemokine production, which recruits immune and inflammatory cell to sustain tumor-associated inflammation." (PMID 29636841, 2018). "Importantly, an interaction that has been demonstrated for human tumor-induced Treg cells is the association of signal transducers and activators of transcription 3 (STAT3) with the β-sheet region of exon 2 in FOXP3fl." (PMID 29593749, 2018). "We further characterized the mechanism underlying this activity and found that inhibition of STAT3 pathway may be involved in its anti-tumor activity." (PMID 29986501, 2018). "The link between STAT3 and lytic susceptibility shows that STAT3 may favor the persistence of tumor cells by limiting lytic activation in EBV-induced tumors." (PMID 32201498, 2018). "We alternately evaluated STAT3 expression in the nucleus and found that the patients with high STAT3 expression in the tumor nucleus were at significantly higher risk of both disease progression (p = 0.003) and cancer-specific mortality than the other patients (p = 0.034)." (PMID 30091994, 2018). "During two-stage skin carcinogenesis, the loss of TC-PTP promoted TPA-induced skin carcinogenesis via the upregulation of STAT3 and AKT signaling, whereas the inhibition of STAT3 or AKT recovered the effects of TC-PTP as a tumor suppressor in TC-PTP deficient cell lines." (PMID 30208623, 2018). "The abnormal activation of STAT3 is linked to tumor stage and prognosis in gastrointestinal tumors." (PMID 30123088, 2018). "STAT3 (signal transducer and activator of transcription 3), part of a group of six varied transcription factors, has been reported to be closely linked with the survival characteristics and aberrant growth of tumor cells." (PMID 29522451, 2018). "Hence, the evaluation of the impact of β-HCH on cellular conditions was carried out on a panel of cell lines representing different human tumor types associated with the expression and activation of specific receptors that are related to STAT3 activity." (PMID 30036966, 2018). "The predictive value of STAT3 was lost over time, but patients with high STAT3 tumor level might have an higher risk of early relapse and could be treated more extensively." (PMID 26910918, 2017).